CHEK2 (checkpoint kinase 2)
Diseases named in the same sentence as CHEK2 in open-access papers (continued):
Sharing a sentence is not in itself a finding about the gene and the disease.
papillary thyroid cancer (14 papers, 2015 to 2025). "One of the co-authors (RK) had a patient with relapsed ALL, whose mother was diagnosed with papillary thyroid carcinoma as an adult, and both the mother and child were found to have a germline CHEK2 mutation." (PMID 39860595, 2025). "CHEK2 is a mediator of anoikis of intestinal epithelial cells and is associated with the progression of papillary thyroid cancer by promoting anoikis." (PMID 37081871, 2023). "In a Czech pediatric population of papillary thyroid cancer patients, 7/84 (8,4%) had a CHEK2 variant." (PMID 35101071, 2022). "In particular, does the CHEK2 c.1100delC mutation convey a higher risk of papillary thyroid cancer and how should we counsel these women?" (PMID 35101071, 2022). "Here it was repeatedly shown that in patients with papillary thyroid carcinoma, the incidence of CHEK2 truncating variants is significantly higher." (PMID 35101071, 2022). "This case led us to review the evidence for an association between mutations in CHEK2 and papillary thyroid cancer." (PMID 35101071, 2022). "CHEK2 germline mutations impair this repair mechanism, causing genomic instability and increasing the risk of various cancers, including papillary thyroid carcinoma (PTC)." (PMID 33530461, 2021). "Another CHEK2 variant, c.470C allele, was shown to increase the risk of papillary thyroid carcinoma in female patients by almost 13-fold (OR = 12.81, p = 0.019)." (PMID 33959510, 2021). "On the other hand, in the described patient, we identified CHEK2-associated typical tumors, like papillary thyroid cancer." (PMID 32570972, 2020). "It has been advocated that chromosome 22q loss is associated with loss of NF2 and CHEK2 tumor suppressors and is influential in the carcinogenesis of papillary thyroid cancer." (PMID 32380731, 2020). "It was reported that the CHEK2 mutation was seen in 73 of 468 (15.6%) unselected patients with papillary thyroid cancer, compared to 28 of 460 (6.0%) age—and sex-matched controls (OR 3.3; p < 0.0001)." (PMID 32570972, 2020). "Is there a relation between risk of papillary thyroid cancer and germline CHEK2 mutations?" (PMID 35101071, 2022). "A weak association was found between the various CHEK2 mutations and papillary thyroid cancer." (PMID 35101071, 2022). "Furthermore, a case-control study reported a CHEK2 mutation in 15.6% of unselected patients with papillary thyroid cancer, compared to 6.0% in age- and sex-matched controls (OR = 3.3, p < 0.0001)." (PMID 33959510, 2021). "The aim of our study was to evaluate whether the CHEK2 mutation was a predictor of poorer clinical course in patients with papillary thyroid cancer." (PMID 33530461, 2021). "Beyond the hereditary cancer genetics, somatic CHEK2 alterations were characterized as mutations that may contribute to tumor progression in papillary thyroid carcinoma." (PMID 33322746, 2020). "Interestingly, a previous study with 468 unselected patients with papillary thyroid cancer found that carriers of truncating CHEK2 mutations had a six-fold increase in risk for a papillary thyroid carcinoma." (PMID 30680046, 2019). "They found the prevalence of overall CHEK2 mutations was 12,24% in patients with papillary thyroid cancer versus 5,53% in matched controls (no statistical analysis available)." (PMID 35101071, 2022). "Intriguingly, the proband had papillary thyroid cancer, recently described in CHEK2 patients." (PMID 32957588, 2020). "Thus, micronodular adrenal hyperplasia, pituitary microadenoma, papillary thyroid cancer, uterine, ovarian, and retroperitoneal (FATWO) lesions are possible after-effects of CHEK2 missense mutation identified in the patient." (PMID 32570972, 2020).
papillary thyroid cancer (continued). "CHEK2 alterations have been reported in a breadth of tumor types, including those not encountered in this case series, including papillary thyroid carcinomas and Wilms tumors." (PMID 36980535, 2023).
brain tumors (13 papers, 2018 to 2024). "This is the first report of the association between the CHEK2 pathogenic variation and brain tumors that warrants further validation in larger cohorts." (PMID 35281821, 2022). "Genetic defects in ARID1A, ARID1B, and CHEK2 have been reported in brain tumors." (PMID 29610389, 2018). "In addition, CHEK2 c.1100delC was identified in Family R, in an unaffected spouse of an unaffected individual, who was not carrying c.1100delC and belonged to the family with brain tumors." (PMID 38773237, 2024).
cervical cancer (13 papers, 2012 to 2026). A primary or metastatic malignant neoplasm involving the cervix. "Moreover, we show that gene silencing or chemical inhibition of the kinases encoded by ATM and CHEK2 reduced the clonogenic and proliferative capacity of cervical cancer-derived cells." (PMID 35745491, 2022). "We show that the down-regulation of ATM, BRCA1, and CHEK2 genes expression selectively affected HPV-positive cervical cancer-derived cells proliferation/viability." (PMID 35745491, 2022). "Genes with known or likely deleterious variants among cervical cancer patients with DDR gene alterations were ATM (n = 3, 2.33%), BRCA2 (n = 3, 2.33%), ATR (n = 2, 1.55%), CHEK2 (n = 2, 1.55%), followed by BRCA1 (n = 1, 0.78%), FANCA (n = 1, 0.78%), MSH6 (n = 1, 0.78%), and RAD51D (n = 1, 0.78%)." (PMID 35071000, 2021). "The results presented here show that the increased expression of CHEK2 and BRCA1 is a common event in the natural history of cervical cancer." (PMID 35745491, 2022). "Overall, we observed higher mRNA levels of CHEK2 and BRCA1 genes in CIN and cervical cancer samples when compared to normal cervix tissue." (PMID 35745491, 2022).
renal cell carcinoma (12 papers, 2016 to 2024). "Subsequent studies with wider cohorts highlighted the peculiar occurrence of the CHEK2 mutation in patients affected by renal cell carcinoma." (PMID 37628581, 2023). "It is noteworthy that the rare variants rs17879961 may impair function of CHEK2, but it was associated with decreased the risk of renal cell cancer." (PMID 27632928, 2016). "The cited authors report that VHL, BAP1, FH, and MET are specific genes that increase the risk of developing renal cell cancer, whereas CHEK2, MUTYH, APC, and STK1 are not typically associated with the development of renal tumours." (PMID 39336594, 2024). "Pathogenic variants in CHEK2 have not been traditionally linked to renal cell carcinoma, but they were the most prevalent germline alteration (3.5%) in a study of 254 advanced renal cell carcinomas." (PMID 35155181, 2021).
Hereditary breast cancer (11 papers, 2001 to 2023). Breast carcinoma that has developed in relatives of patients with history of breast carcinoma. "On the other hand, our finding of stronger statistical evidence for genes known to be associated with hereditary breast cancer (CHEK2, ATM and BRCA2) is novel." (PMID 36816149, 2023). "Recently, in France, 16 CHEK2 mutations were found in 507 cases of BRCA1/2-negative hereditary breast cancer." (PMID 24986639, 2014). "When pathogenic/likely pathogenic mutations were aggregated within each gene, the association was confirmed for three genes in the UKB at p < 0.0056 (Bonferroni correction for nine tests), including CHEK2, ATM and BRCA2, all also known to be associated with hereditary breast cancer." (PMID 36816149, 2023).
lung adenocarcinoma (11 papers, 2014 to 2025). A carcinoma that arises from the lung and is characterized by the presence of malignant glandular epithelial cells. "The CHEK2 K373E variant was split among many cancer types, but 17 patients with lung adenocarcinoma carried it." (PMID 28743916, 2017). "The prevalence in our cohort also exceeds that of Finnish patients in the early‐stage lung adenocarcinoma cohort, where all CHEK2 alterations had a prevalence of 3.7%, and that of the MSKCC cohort of advanced NSCLC (< 1%)." (PMID 41015991, 2025). "We identified several targetable pathways in EGFR/KRAS/ALK-negative lung adenocarcinoma including PI3K/mTOR signaling (TSC1, PIK3CA, AKT2), receptor tyrosine kinase signaling (ERBB4), cell cycle regulation (CHEK2, CDC27), and DNA repair (PARP4)." (PMID 24576404, 2014).
hereditary cancer syndromes (10 papers, 2020 to 2025). "Additionally, CHEK2-Associated Hereditary Cancer Syndrome and cancer predisposition associated with BRIP1 mutations may represent conditions with a potential association with MM risk." (PMID 41331641, 2025). "Overall, 86 (36.4%) of the 236 patients who received genetic testing results tested positive for an LPV/PV in a hereditary cancer syndrome gene; one patient tested positive for two LPV/PVs (SDHB and CHEK2), resulting in a total of 87 LPV/PVs identified." (PMID 39539798, 2024).
meningioma (10 papers, 2016 to 2025). A generally slow growing tumor attached to the dura mater. "Two recurring meningiomas had the inactivation of cell cycle inhibitors; one (13M) had a CHEK2 truncating mutation, coupled with the deletion of the second allele, the other (21M) had CDKN2A/B homozygous deletion." (PMID 33670055, 2021). "Notably, the genomic profiling for Individual 2, who presented with an atypical meningioma with a chromosome 22 loss, resulted in loss of the mutant CHEK2 allele harboring the c.1100del variant in the tumor and with retention of the wild-type CHEK2 allele in a single-copy state." (PMID 36980535, 2023). "In accordance with this, in our series, the meningioma with the bi-allelic inactivation of CHEK2 had multiple chromosomal losses and CNL, and it recurred during the follow-up." (PMID 33670055, 2021). "As a result, most of the previously reported meningioma mutations (NF2, TRAF7, NOTCH2, SMARCB1, CHEK2 and AKT1) were also detected in this study." (PMID 28177878, 2017). "Three cases (case 1, 3 & 7) carried loss of chromosome 22 and deletions of three known meningioma-driver genes (NF2, CHEK2 and SMARCB1)." (PMID 28177878, 2017). "Alternative splicing and frequent codeletion of CHEK2 with NF2 in meningiomas harbouring chromosome 22q deletions impaired DNA repair in their study and increased chromosomal instability, thus promoting meningioma progression." (PMID 27429002, 2016). "Co-deletion of CHEK2 and NF2 (both on chromosome 22) was reported to contribute to meningioma pathogenesis and genomic instability." (PMID 36980535, 2023).
metastatic prostate carcinoma (10 papers, 2017 to 2024). A carcinoma that arises from the prostate gland and has spread to other anatomic sites. "CHEK2 variants are found in fewer than one percent of the general population (0.61% in the Exome Aggregation Consortium) and in two percent of men with metastatic prostate cancer, giving a relative risk for metastatic prostate cancer of 3.1 (95% CI: 1.5–5.6), p = 0.000256." (PMID 35732815, 2022). "In metastatic prostate cancer, an expanded HRD panel included patients with mutations to BRCA1, BRCA2, ATM, FANCA, CHEK2, PALB2, NBN, or HDAC2." (PMID 35205643, 2022).
Wilms tumor (10 papers, 2018 to 2025). An embryonal neoplasm characterized by the presence of epithelial, mesenchymal, and blastema components. "Of note, such efforts have documented cases of Wilms tumour with pathogenic germline mutations in genes conferring increased risk to adult epithelial cancers, such as CHEK2 or BRCA2." (PMID 39665570, 2025). "Unexpectedly, Gadd and colleagues identified germline CHEK2 variants in 3/117 (2.6%) and 8/651 (1.2%) patients with Wilms tumors in their discovery and validation sets, respectively." (PMID 33322746, 2020). "The genomic studies of familial cases of Wilms tumor have allowed the identification of germline variants in the DICER1, WT1 (WT1 Transcription Factor), CHEK2 (Checkpoint Kinase 2), and PALB2 (Partner And Localizer Of BRCA2) genes." (PMID 36295546, 2022).
liver cancer (9 papers, 2015 to 2026). An epithelial or non-epithelial malignant neoplasm that arises from the liver. "Ma and Zhang found that diosmetin inhibits the proliferation of liver cancer cells by targeting checkpoint kinase 2 (Chk2) and promotes cancer cell apoptosis and cell cycle arrest." (PMID 35646118, 2022). "In sinularin-treated liver cancer (HepG2) cells, Ataxia telangiectasia mutated (ATM)/checkpoint kinase 2 (Chk2) was activated to induce DNA damages in terms of γH2AX." (PMID 29642488, 2018).
medulloblastoma (9 papers, 2007 to 2025). A malignant, invasive embryonal neoplasm arising from the cerebellum. "Patient #5 with suspected Li–Fraumeni syndrome was diagnosed with medulloblastoma at an early age and a CHEK2 variant." (PMID 38139220, 2023). "CHEK2 and AGL require follow-up in future studies to determine their relationship with susceptibility to medulloblastoma." (PMID 39184053, 2024). "CHEK2, which has not been previously associated with medulloblastoma, had nominally more P/LP variants when compared to controls (3 European cases; p=0.012)." (PMID 39184053, 2024). "There were two genes (CHEK2 and AGL) that had P/LP variants enriched in medulloblastoma cases compared to controls that were not previously associated with medulloblastoma." (PMID 39184053, 2024). "Similar studies in patients with medulloblastoma have not been executed, and preclinical data imply CHEK2 alterations as a potential target in this disease." (PMID 38139220, 2023).
myeloid malignancies (8 papers, 2022 to 2025). "Among those with other germline P/LP CHEK2 alleles, 36% (13/36) had myeloid malignancies, 28% (10/36) had lymphoid malignancies, and 6% (2/36) had both." (PMID 40335619, 2025). "P/LP likely germline variants in genes that have previously been associated with adult myeloid malignancy were found in 16 patients (4.4%), including ATM, BRCA2, CHEK2, and TNFRSF13B." (PMID 40766138, 2025). "In the subset of patients with CHEK2 p.I157T (55%, 44/80), 77% (34/44) had a HM; 56% (19/34) had a myeloid malignancy, 41% (14/34) had a lymphoid malignancy, and 3% (1/34) had both myeloid and lymphoid malignancies." (PMID 40335619, 2025). "Among all probands and family members (patients) with CHEK2-path, 74% (59/80) had a diagnosed HM; 54% (32/59) had a myeloid malignancy, 41% (24/59) had a lymphoid malignancy, and 5% (3/59) had both myeloid and lymphoid malignancies." (PMID 40335619, 2025). "For myeloid malignancies, CHEK2 status was also significant on multivariate analysis (OR 2.34, 95% CI 1.31–3.82, P = 0.002)." (PMID 40335619, 2025). "Among CHEK2 p.I157T carriers, 43% (19/44) had myeloid malignancies, 32% (14/44) had lymphoid malignancies, and 2% (1/44) had both." (PMID 40335619, 2025). "Among CHEK2 p.I157T patients with myeloid malignancies, 40% (8/20) had a previous solid organ malignancy; 15% (3/20) had surgical treatment only, and 25% (5/20) had chemotherapy or radiation, one of whom had radiation for an antecedent Hodgkin lymphoma." (PMID 40335619, 2025). "Less than half of the myeloid malignancies in CHEK2 p.I157T patients were second malignancies (42%, 8/19)." (PMID 40335619, 2025). "Among all diagnosed myeloid malignancies in CHEK2-path patients (N = 35), 34% (12/35) had AML, 26% (9/35) had MDS, 31% (11/35) had MPN, and 9% (3/35) had MDS/MPN." (PMID 40335619, 2025).
rectal cancer (8 papers, 2013 to 2023). A primary or metastatic malignant neoplasm that affects the rectum. "However, only CHEK2 was associated with both significantly higher expression in tumor tissue and significant impact on the outcome of patients with rectal cancer." (PMID 36164349, 2022). "This suggests that CHEK2 may be a core regulatory kinase in rectal cancer, exerting its biological effect by regulating the expression of FUT4 co-expression genes." (PMID 36164349, 2022). "The results of this study propose two potential genes as target candidates for the precise treatment of rectal cancer: the immune microenvironment regulatory gene FUT4 and kinase family member CHEK2." (PMID 36164349, 2022).
renal carcinoma (8 papers, 2006 to 2026). A carcinoma arising from the epithelium of the renal parenchyma or the renal pelvis. "CHEK2 was associated with renal cancer (OR at 7.14; 95% CI 1.74–29.6; p < 0.003) in our study in comparison to the gnomAD control population." (PMID 38002934, 2023). "An OR associated with CHEK2 ranges between 2% and 3%, according to studies with a restricted confidence interval, which corresponds to a lifetime renal cancer risk between 2.6–3.6% and 3.9–5.4%." (PMID 38002934, 2023). "Later, numerous studies reported that CHEK2 is a multiorgan cancer susceptibility gene, such as breast, ovarian, prostate, and renal cancer." (PMID 34549727, 2021). "A study of the management of renal cancer risk for CHEK2 pathogenic variant carriers is needed." (PMID 38002934, 2023). "CHEK2 seems to be associated with renal cancer risk with low penetrance." (PMID 38002934, 2023). "Therefore, our finding adds an important piece of evidence to the literature, leading to the need of new more in-depth research to evaluate the role of CHEK2 in renal cancer." (PMID 37628581, 2023). "At present, CHEK2 is not included in renal cancer panel genes, and no management is recommended for these patients." (PMID 38002934, 2023).
serous ovarian cancer (8 papers, 2010 to 2025). "Two CHEK2 pathogenic variants were found in patients with high-grade serous ovarian cancer." (PMID 36555431, 2022). "Intriguingly, CHEK2 p.Lys373Glu is strongly correlated with patients’ progression-free survival in high-grade serous ovarian carcinoma post-olaparib treatment." (PMID 41152984, 2025).
clear cell renal cell carcinoma (7 papers, 2020 to 2025). "It is noteworthy that two CHEK2 mutations occurred in two individuals with a diagnosis of clear cell renal cell carcinoma (ccRCC) and in situ melanoma, respectively." (PMID 37628581, 2023). "Furthermore, the miR-577/CHEK2/FOXM1 axis has been linked to radiation resistance in clear cell renal cell carcinoma." (PMID 41413918, 2025). "Moreover, the segregation analysis of PVs and LPVs into first-degree relatives allowed the detection of CHEK2 variant carriers diagnosed with in situ melanoma and clear cell renal cell carcinoma (ccRCC), respectively." (PMID 37628581, 2023). "LINC01094 facilitates clear cell renal cell carcinoma radioresistance by targeting the miR-577/CHEK2/FOXM1 axis." (PMID 35047414, 2021). "Targeting the miR-577/CHEK2/FOXM1 axis, LINC01094 promotes radioresistance in clear cell renal cell carcinoma (ccRCC)." (PMID 36568382, 2022).